INSIG1 (insulin induced gene 1)
Diseases named in the same sentence as INSIG1 in open-access papers (continued):
Sharing a sentence is not in itself a finding about the gene and the disease.
gout (1 paper, 2020). A condition characterized by painful swelling of the joints, which is caused by deposition of urate crystals. "In conclusion, this study provided evidence of aberrant methylation changes of PGGT1B, INSIG1, ANGPTL2, JNK1, UBAP1, RAPTOR, and CNTN5 in gout." (PMID 32630231, 2020). "In gout patients, seven aberrant DNA methylation sites that were mapped to seven genes (PGGT1B, INSIG1, ANGPTL2, JNK1, UBAP1, RAPTOR, and CNTN5) and survived genetic and meQTL analyses or causal inference tests were discovered." (PMID 32630231, 2020). "Interestingly, some studies explored the relationships between molecules, INSIG1 and ANGPTL2, and gout." (PMID 32630231, 2020). "If common genetic variation did not contribute to the epigenetic associations of PGGT1B, INSIG1, ANGPTL2, JNK1, and CNTN5 with gout, it would be interesting to clarify mechanisms underlying the differential methylation of these CpG sites in gout." (PMID 32630231, 2020). "Six (PGGT1B, INSIG1, ANGPTL2, JNK1, UBAP1, and RAPTOR) were novel genes in the field of gout." (PMID 32630231, 2020). "Given the roles of PGGT1B, INSIG1, ANGPTL2, JNK1, UBAP1, RAPTOR, and CNTN5 in regulating IL-1β or gouty inflammation and differential methylation of these genes in gout, the next important topic is the consequence of manipulating the respective signaling pathways." (PMID 32630231, 2020). "Moreover, measuring transcription factors identified in this study and chromatin immunoprecipitation (ChIP) for these transcription factors would provide more clues about the mechanistic link between PGGT1B, INSIG1, ANGPTL2, JNK1, UBAP1, RAPTOR, and CNTN5 methylation and gout." (PMID 32630231, 2020). "Taken together, these results suggested that relationships between PGGT1B, INSIG1, ANGPTL2, JNK1, UBAP1, RAPTOR, and CNTN5 methylation and gout were not confounded by genetic mediators." (PMID 32630231, 2020).
HCMV infection (1 paper, 2013). "Our data demonstrate that the induction of PERK during HCMV infection is necessary for full activation of lipogenesis; this effect appears to be mediated by limiting the levels of Insig1 thus freeing SREBP1-SCAP complexes for SREBP1 processing." (PMID 23592989, 2013). "In contrast, HCMV infection of these cells showed increased Insig1-Myc levels in the shGFP expressing cells, presumably due to HCMV-mediated transcriptional activation of the major immediate early promoter used in this expression vector." (PMID 23592989, 2013). "Due to the lack of appropriate antibody to detect endogenous Insig1 in human cells, we introduced Myc-tagged Insig1 to examine if Insig1 protein levels could be altered due to the increase of PERK expression in HCMV infection." (PMID 23592989, 2013).
Hypertension (1 paper, 2024). The presence of chronic increased pressure in the systemic arterial system. "Furthermore, Insig1 expression was low, and Aldh1a1 expression was high in CKD patients with hypertension." (PMID 38806641, 2024).
liver cancer (1 paper, 2023). An epithelial or non-epithelial malignant neoplasm that arises from the liver. "In Huh7 liver cancer cells, miR-122 regulates the use of polyadenylation sites in INSIG1 mRNA and inhibits the translation of INSIG1 isoform mRNA, thereby affecting the activation of SREBPs." (PMID 36969840, 2023).
lung adenocarcinoma (1 paper, 2025). A carcinoma that arises from the lung and is characterized by the presence of malignant glandular epithelial cells. "In lung adenocarcinoma (LUAD), piRNA‐137463 silences the expression of the cholesterol synthesis inhibitor INSIG1 through the LOC100128494/miR‐24‐3p/INSIG1 axis, thereby enhancing cholesterol biosynthesis." (PMID 39692168, 2025).
nonalcoholic steatohepatitis (1 paper, 2021). "The SCAP/SREBP/INSIG1 trio promotes hepatic lipid remodeling to protect the liver from lipotoxic insults associated with the progression of nonalcoholic steatohepatitis progression." (PMID 34987591, 2021).
osteosarcoma (1 paper, 2025). A usually aggressive malignant bone-forming mesenchymal neoplasm, predominantly affecting adolescents and young adults. "LPCAT1 or SOX2 overexpression promoted malignant behaviors and cholesterol metabolism (free cholesterol/total cholesterol levels, SREBP1/INSIG1 expression) of osteosarcoma cells, while shSOX2 or shLPCAT1 did the opposite." (PMID 41358198, 2025).
pulmonary fibrosis (1 paper, 2014). Chronic progressive interstitial lung disorder characterized by the replacement of the lung tissue by connective tissue, leading to progressive dyspnea, respiratory failure, or right heart failure. "miR29 is associated with the pathogenesis of pulmonary fibrosis and regulates pro-inflammatory cytokine secretion by targeting Insig1, Srebf1 and Lpl." (PMID 24806461, 2014).
renal fibrosis (1 paper, 2024). A final common manifestation of a wide variety of chronic kidney diseases characterized by glomerulosclerosis and tubulointerstitial fibrosis. "We discovered the pathogenic effect of PTC-specific Insig1 deficiency on renal fibrosis in vivo and in vitro." (PMID 38806641, 2024). "All these in vivo and in vitro experimental data strongly suggested that tubular Insig1 deficiency aggravated renal fibrosis in CKD." (PMID 38806641, 2024). "Then, utilizing isolated renal tubule tissue, we conducted a bulk RNA-seq analysis to examine differences in gene expression between Insig1flox/flox and Insig1ΔKap mouse PTCs to better understand the underlying mechanism by which Insig1 prevents renal fibrosis." (PMID 38806641, 2024). "Then, we investigated the role of Insig1 in another renal fibrosis model prepared with Insig1flox/flox and Insig1ΔKap mice treated with 5/6 Nx for 16 weeks." (PMID 38806641, 2024). "Based on the results of genetic, in vivo, in vitro, and pharmacological investigations, this study revealed that PTC-specific Insig1 plays a significant role in the progression of renal fibrosis in CKD." (PMID 38806641, 2024). "To elucidate the role of Insig1 in CKD renal fibrosis, we subjected Insig1ΔKap and Insig1flox/flox mice to UUO for 14 days to generate classical renal fibrosis model mice." (PMID 38806641, 2024). "As Insig1 regulates lipid metabolism, we first examined whether Insig1 deletion exacerbates UUO-induced renal fibrosis mediated through its effect on lipid metabolism." (PMID 38806641, 2024). "Here, we discovered that tubular Insig1 deficiency, rather than fibroblast Insig1 deficiency, plays a detrimental role in the pathogenesis of renal fibrosis in vivo and in vitro." (PMID 38806641, 2024). "In contrast to the findings with Insig1ΔKap mice, fibroblast deficiency of Insig1 did not worsen UUO-induced renal fibrosis, as evidenced by unchanged collagen deposition and fibrotic indicator (Fn, Acta2, Col3a1, and Vim) mRNA expressions in the kidneys." (PMID 38806641, 2024). "Insulin-induced gene 1 (Insig1) is one of the branch-dependent genes involved in controlling this process, although its role in renal fibrosis is unknown." (PMID 38806641, 2024). "Because fibroblast activation plays a crucial role in renal fibrosis, we created fibroblast-specific Insig1-knockout (Insig1ΔS100A4) mice, which had ~85% reduction in Insig1 expression in cultured primary renal interstitial fibroblasts than those of Insig1flox/flox mice." (PMID 38806641, 2024). "Insig1 deletion boosted SREBP1 nuclear localization, increasing Aldh1a1 transcriptional activity, causing excessive NAD+ consumption and ER enlargement, and accelerating renal fibrosis." (PMID 38806641, 2024). "Overexpression of Insig1 profoundly inhibited renal fibrosis." (PMID 38806641, 2024). "Mechanistically, Insig1 deletion in PTCs boosted SREBP1 nuclear localization, increasing Aldh1a1 transcriptional activity, causing excessive NAD+ consumption and ER enlargement, as well as accelerating renal fibrosis." (PMID 38806641, 2024). "In addition, Insig1 deficiency in fibroblast did not worsen renal fibrosis following the 5/6 Nx challenge." (PMID 38806641, 2024). "Furthermore, we described the pathogenic impact of PTC-specific Insig1 deficiency on renal fibrosis in vivo and in vitro, as opposed to fibroblast-specific Insig1 deficiency." (PMID 38806641, 2024). "We used PTCs-specific and fibroblast-specific Insig1-knockout mice and whole-body Aldh1a1-knockout mice subjected to UUO or 5/6 nephrectomy (5/6 Nx) to evaluate the importance of PTC-specific Insig1 in conferred protection against renal fibrosis and the maintenance of NAD+ homeostasis." (PMID 38806641, 2024).
schizophrenia (1 paper, 2024). A major psychotic disorder characterized by abnormalities in the perception or expression of reality. "The mutation frequencies of INSIG1 and SREBF1 were both lower than 10% in male and female schizophrenia patients." (PMID 38760414, 2024).
Stroke (1 paper, 2024). Sudden impairment of blood flow to a part of the brain due to occlusion or rupture of an artery to the brain. "Moreover, up- and downregulated genes were commonly confirmed by both configurations of the HD-tDCS-FN application, including insulin-induced gene 1 (Insig1) and bcl-2-associated athanogene 5 (Bag5), which are related to stroke insults." (PMID 38389833, 2024).
tumor (16 papers, 2015 to 2026). "This is reinforced by the observation that genes (Igfbp1 and Igfbp2) encoding insulin like growth factor binding proteins and insulin-induced gene 1 (Insig1) were downregulated in tumor of KO mice." (PMID 34685767, 2021). "Given that NF2 is a well-established tumor suppressor gene, we focused on subsequent analyses of INSIG1 and ACSL3." (PMID 41564380, 2026). "Consistently, the knock‐down of LOC100128494 or INSIG1 also reversed the effect of piRNA‐137463 silencing on T cell‐mediated anti‐tumor immunity." (PMID 39692168, 2025). "In contrast, the Insig1/2 loop 1 peptide inhibited tumor growth and reduced tumor weight and volume." (PMID 40959854, 2025). "To examine the effect of the Insig1/2 loop 1 peptide on tumor growth, we subcutaneously injected Huh7 cells into nude mice." (PMID 40959854, 2025). "In addition, combination treatment with lenvatinib and the Insig1/2 loop 1 peptide exhibited an additive tumor‐inhibitory effect." (PMID 40959854, 2025). "In our study, we demonstrated that CRC-derived exosomal miR-1246 activates HSCs, and that silencing the target gene INSIG1 leads to metabolic reprogramming within the tumor microenvironment (TME), contributing to the establishment of a metastatic landscape in CRLM." (PMID 39979806, 2025). "In addition, Oil Red O staining revealed that the Insig1/2 loop 1 peptide reduced lipid accumulation in tumor tissues." (PMID 40959854, 2025). "In addition, Insig1/2 loop 1 peptide injection inhibited intrahepatically injected tumor cell growth in the liver and prolonged mouse survival." (PMID 40959854, 2025). "Importantly, the reduction in lipid levels in tumors by semaglutide combined with the inhibition of de novo lipid synthesis via the Insig1/2 loop 1 peptide produced an additive tumor‐inhibiting effect and prolonged mouse survival." (PMID 40959854, 2025). "EGFR/INSIG-1/SREBP-1 signaling is critical for tumor growth, maintenance, and metastasis." (PMID 34518524, 2021). "IHC analyses and Oil Red O staining of tumor tissues revealed that semaglutide administration decreased high‐fat diet‐increased lipid levels and Ki67 expression in tumor tissues, and this reduction was further promoted by combined treatment with the Insig1/2 loop 1 peptide." (PMID 40959854, 2025). "Moreover, the levels of PCK1 pS90, Insig1 pS207/Insig2 pS151, and SREBP-1 are associated with the tumor, metastasis stage, and progression of esophageal squamous cell carcinoma, suggesting PCK1 activity-regulated SREBP-1 as a potential target for the diagnosis and treatment of esophageal cancer." (PMID 35912181, 2022). "Regardless of Anti‐IgG or Anti‐PD‐1 treatment, Anta‐137463 treatment increased the staining level of INSIG1 and reduced the level of SREBP2 in serial sections of xenograft tumor tissues." (PMID 39692168, 2025). "As for LUAD, we found logFC value 0.33 (adj.P.Val = 6.15 × 10−5) for INSIG1 expression (GSE63459 consisting of 30 paired adjacent and tumor tissue samples)." (PMID 34440098, 2021). "Intravenous delivery of the Insig1/2 loop 1 peptide effectively attenuated tumor growth, prolonged mouse survival, inhibited the PCK1‐Insig‐SREBP‐lipid production axis, and increased cell apoptosis in tumor tissues." (PMID 40959854, 2025). "Immunohistochemistry (IHC) assays revealed higher levels of INSIG1 expression in Anta‐137463 group (II) compared to g Anta‐NC group (I) whereas the expression of SREBP2, FLOT1, and Ki67 was markedly diminished within the xenograft tumor tissues." (PMID 39692168, 2025). "Intravenous administration of engineered liposomal nanoparticles (LNP)‐encapsulated Insig1/2 loop 1 peptide effectively suppresses tumor growth and extends mouse survival without apparent adverse effects." (PMID 40959854, 2025). "PCK1 with protein kinase activity can phosphorylate INSIG1/2, which leads to impaired binding of INSIG1/2 with intracellular lipids, thus promoting the activation of the SREBP signaling pathway and lipid synthesis of tumor cells." (PMID 36387147, 2022).
tumor (continued). "The intravenous injection of LNPs (136.83 nm, 1:1 ratio of TAT and cRGD) encapsulating the Insig1/2 loop 1 peptide (LNP@Insig1/2 loop 1 peptide) or LNPs with a scramble peptide (LNP@scramble) into mice revealed that the LNPs with a scramble peptide had no obvious effect on tumor growth." (PMID 40959854, 2025). "In addition, the expression levels of AKT pS473, PCK1 pS90, INSIG1 pS207/INSIG2 pS151, and nuclear SREBP1 are higher in 451 analyzed human NSCLC specimens than in their adjacent normal tissues and positively correlated with each other in the tumor specimens." (PMID 33842305, 2021). "Consequently, this treatment abrogates PCK1‐mediated phosphorylation of Insig1 at S207 and Insig2 at S151, reduces the nuclear accumulation of SREBP1, and decreases SREBP1 activity‐dependent expression of lipid synthesis genes, lipid accumulation, and tumor cell proliferation." (PMID 40959854, 2025).
cancer (13 papers, 2017 to 2025). A tumor composed of atypical neoplastic, often pleomorphic cells that invade other tissues. "INSIG1 has been implicated in epithelial-mesenchymal transition, which is also one of the hallmarks of cancer." (PMID 33105711, 2020). "More evidence for a non-enzymatic role by PCK isoforms, beyond GNG, is the recently reported protein kinase activity of PCK1 resulting in the phosphorylation of INSIG1/2 proteins and subsequent promotion of cancer cell growth." (PMID 38783087, 2024). "Although the decreased INSIG1 expression in cancers correlated with methylation at the edge of CpG islands in the promoter region, the methylation was likely a secondary change." (PMID 39861074, 2024). "Combinatory treatment with Sorafenib, mostly resulted with downregulation of hub proteins JUN, INSIG1, MDM2 and SOX9 associated with cancer cells." (PMID 35331184, 2022). "Reduced expression of INSIG1 in PGCC relative to parental cancer cells may reflect their higher need for cholesterol." (PMID 35624221, 2022). "Thus, a decrease in INSIG1 protein reflects the altered cholesterol in PGCC compared to parental cancer cells, which represents another parallel between PGCC and the pre-implantation embryos." (PMID 35624221, 2022). "Theoretically, in this machinery, a cancer-driven reduction of INSIG1 expression could dysregulate HMGCR proteolytic degradation under cholesterol-replete conditions and promote excess cholesterol accumulation." (PMID 34440098, 2021). "The correlation between the expression of INSIG1 as well as AKAP12 and their corresponding prognosis in cancer patients receiving BV was analyzed applying the Kaplan–Meier plotter database and two GEO datasets." (PMID 36110213, 2022). "The hypoxia-induced EMT depends on the demethylation of a subset of genes (with a major role played by INSIG1, insulin-induced gene 1) by the TET1 dioxygenase, induced by hypoxia in multiple cancer cell lines." (PMID 32806509, 2020). "Analysis also revealed INSIG1 and NROB2 as the top inhibited upstream regulators among the benign cancers." (PMID 30517191, 2018). "Similarly, the expression of SLC3A2, TUBA1B, TUBA1C, TUBB, FSTL1, and INSIG1 was affected by FIRΔexon2, suggesting that FIR and FIRΔexon2 engage in the transcription of various cancer-related mRNAs." (PMID 38139171, 2023). "Therefore, a possible scenario entails that inhibition of INSIG1 expression by miR-183-5p and miR-210-3p increases DCT resistance by sustaining cancer cell survival and activating lipogenesis." (PMID 38065937, 2023). "Nevertheless, it is interesting that a positive Pearson correlation (R > 0.6) between up-regulated INSIG1 and HMGCR expression in the TCGA-READ dataset may indicate the cancer-type specific expression of INSIG1." (PMID 34440098, 2021). "Although the fold-change in expression of HMGCR and INSIG1 mRNA was less than 2, we were interested in determining whether the observed pattern was idiosyncratic to PPC1 cells or if it was observed in PGCC generated from other cancer cells." (PMID 35624221, 2022). "Compared to parental cancer cells, PGCC-independent of ASAH1 inhibition- had lower expression of INSIG1 protein, more efficiently effluxed cholesterol, and expressed high levels of SR-B1." (PMID 35624221, 2022).
infection (7 papers, 2009 to 2021). The state of being infected such as from the introduction of a foreign agent such as serum, vaccine, antigenic substance or organism. "The expression level of INSIG-1 early post-infection increased in the SC and TC chimpanzees while it varied only slightly within the first eighteen days post-infection in the PS chimpanzee." (PMID 19149867, 2009). "Early post-infection, the expression level of INSIG-1 increased in the SC and TC chimpanzees and slightly decreased in the PS chimpanzee, suggesting that this gene acts as an early metabolic predictor of outcome." (PMID 19149867, 2009). "In summary, our data provided the time-specific comprehensive information of circRNAs, miRNAs and mRNAs in response to NDV LaSota vaccine infection in thymic tissues of Chinese Partridge Shank chickens and elucidated the vital roles of gga-miR-6631-5p/INSIG1 axis in LaSota NDV replication." (PMID 33986327, 2021). "The data suggest that increasing the levels of Insig1 in the infected cells can overcome the effects of induced PERK during infection; the further depletion of PERK in the Insig1-Myc transfected cells had little additional effect." (PMID 23592989, 2013).
inflammation (2 papers, 2014 to 2019). Aberrant reaction of the microcirculation characterized by movement of fluid and leukocytes from the blood into extravascular tissues. "We found strong similarity of the aged type-2 phenotype with the phenotype in Insig1/2 knockout mice that accumulated neutral lipids, accompanied by lipotoxicity-related lung inflammation and tissue remodeling." (PMID 30814501, 2019). "Conversely, deletion of the Insig1 and Insig2 genes (Insig1/2Δ/Δ) activated SREBP-mediated lipogenesis in respiratory epithelial cells resulting in lipotoxicity-related lung inflammation and tissue remodeling in adult mice." (PMID 24806461, 2014).
kidney diseases (2 papers, 2024 to 2025). "Consistent with its alteration in the UUO mouse model, Insig1 was downregulated in kidney biopsies of children with kidney disease compared to controls." (PMID 38806641, 2024).